ZNF185 (zinc finger protein 185 with LIM domain)
Diseases named in the same sentence as ZNF185 in open-access papers (continued):
Sharing a sentence is not in itself a finding about the gene and the disease.
tumor (continued). "Our data indicate that while a decrease in E-cadherin is generally a useful prognostic biomarker in different epithelial tumour types, loss of ZNF185 is strongly associated with late tumour stages and poorly differentiated head and neck, possibly oesophageal and cervical, SCC tumours." (PMID 30337687, 2019). "In pancreatic ductal adenocarcinoma, ZNF185 and SERTAD2 are tumor immune targets, providing new ideas for treatment of tumor immune invasion." (PMID 37396042, 2023). "According to the previous literature, the positive prognostic values of ZNF185, SRD5A2, and AOX1 are expressed in normal tissues than in tumors, but their methylation levels in tumor tissues are higher than those in normal tissues." (PMID 35813821, 2022). "Among them, DPY30, EREG, PLA2G16, ZNF185, PADI1, INPP4B and AP1S3 have been reported to be involved in tumor genesis and progression, and they were significantly positively correlated with risk score." (PMID 34090418, 2021). "Other ZNF members including ZNF281, ZNF185 and ZNF750 serve as oncogenes or tumor suppressor genes in different cancers." (PMID 34670480, 2021). "ZNF185 could be included as a prognostic marker to assess the differentiation state in oesophageal, cervical and head and neck SCC tumours." (PMID 30337687, 2019).
cancer (15 papers, 2007 to 2025). A tumor composed of atypical neoplastic, often pleomorphic cells that invade other tissues. "Further studies on the diagnostic and prognostic value of ZNF185 in cancer are warranted." (PMID 30337687, 2019). "In the existing literature, studies investigating the relationship between ZNF185 and the clinical characteristics of cancer have reported that ZNF185 plays different roles depending on the type of cancer." (PMID 40136427, 2025). "We also observed that ZNF185 was mainly low (56.3%, 45/80) in the normal pancreas and high (51.2%, 41/80) in cancer." (PMID 32565799, 2020). "Our findings indicate that ZNF185 is part of the deregulated programme that affects SCC cancer cell behaviour." (PMID 30337687, 2019). "A possible mechanism by which ZNF185 exerts its function in cancer biology is through the interaction with actin filaments." (PMID 29152378, 2017). "The importance of ZNF185 in cancer progression is highlighted by its reduced expression in intermediate, high-grade, and metastatic prostate tumours compared with normal tissue." (PMID 29152378, 2017). "Our studies expand the knowledge about the role of p63 in epithelial biology and identify a new factor, ZNF185, that could improve cancer diagnosis, prognosis and therapy." (PMID 30337687, 2019). "Thus far, the role of ZNF185 in cancers remains controversial." (PMID 34421347, 2021). "Overall, these findings show the promise of EPZ004777 as a therapeutic agent, with TPBG, ZNF185, and SNX19 serving as focal points for further research to refine its application in cancer treatment." (PMID 40136427, 2025). "We found that the mRNA expression of IL7R, COL22A1, ZNF185, and SRD5A2 were upregulated in cancer tissues, while PTGS2 and CLDN1 were higher in normal tissues, consistent with our previous analysis." (PMID 35813821, 2022). "The χ2 test showed significant differences in the expression of HEATR1 (χ2 = 37.143, P < 0.001), ZNF185 (χ2 = 20.077, P < 0.001), and SMAD4 (χ2 = 23.309, P < 0.001) between the cancer and the normal pancreas." (PMID 32565799, 2020). "Most of these genes have not been previously reported in HCC, and BTBD17, MIR6089, ZNF205-AS1 and ZP1 have not previously been linked to cancer; only two genes (DAB2IP and ZNF185) have been reported in HCC." (PMID 27768594, 2016). "ZNF185 involvement in pathologies, such as cancer, has not been completely investigated yet." (PMID 30446632, 2018). "The absence of ZNF185 in ESCC, especially in poorly differentiated cells, suggests that p63 downregulates E-Cadherin via ZNF185 in cancer." (PMID 36291586, 2022).
ZNF185 also shares sentences with these, for which no sentence is quoted: breast carcinoma (2 papers); lung carcinoma (2); adenoid cystic carcinoma (1); bladder cancer (1); chromophobe renal cell carcinoma (1); colorectal cancer (1); cutaneous squamous cell carcinoma (1); head and neck carcinoma (1); lymph node metastasis (1); metastasis (1); metastatic disease (1); non-small cell lung carcinoma (1); ovarian carcinoma (1); prostate adenocarcinoma (1).